HIF1A (hypoxia inducible factor 1 subunit alpha)
Diseases named in the same sentence as HIF1A in open-access papers (continued):
Sharing a sentence is not in itself a finding about the gene and the disease.
myopia (continued). "In our study, the expression of HIF-1α was high at 2, 4, and 6 weeks of myopia induction." (PMID 40351473, 2025). "Inhibitors of the MAPK/ERK pathway and molecules modulating its interactions with pathways like PI3K/AKT and HIF-1α could offer new strategies for preventing or slowing myopia progression." (PMID 40933557, 2025). "This study aims to determine whether atropine inhibits myopia progression by improving choroidal microcirculation and scleral hypoxia, inhibiting the HIF-1α signaling pathway, and targeting MRs on scleral fibroblasts to inhibit ECM production and remodeling." (PMID 40183102, 2025). "Then, intestinal flora may weaken the scleral structure by increasing HIF-1α levels, leading to myopia development." (PMID 36961150, 2023). "To explore whether the retina is hypoxic in myopia and whether the lncRNA-XR_002792574.1/miR-760-3p/Adcy1 axis in RGCs is related to retinal hypoxia, we detected the expression of HIF-1a in the retina." (PMID 37932794, 2023). "During myopia, the accumulation of HIF-1α in scleral microenvironment may trigger myofibroblast transdifferentiation, which is characterized by reduced collagen biosynthesis and increased α-SMA expression." (PMID 37355654, 2023). "Notably, emerging evidence has suggested the role of Hif1a and scleral hypoxia in myopia and refractive errors." (PMID 37449273, 2023). "Scleral hypoxia mediated by Hif1a may contribute to myopia by promoting collagen degradation and extracellular matrix remodeling." (PMID 37449273, 2023). "The downregulation of Hsp90aa1 after atropine treatment may reduce HIF1α, thereby slowing down myopia progression." (PMID 35153787, 2022). "Oxidative stress has been implicated in different ocular tissues in myopic eyes, such as the retina and sclera, which can explain the complex signaling pathways involved in the regulation of myopia, particularly the hypoxia-inducible factor-1 alpha (HIF-1α) signaling pathway." (PMID 34660571, 2021). "Thus, targeting the HIF-1α signaling pathway could represent a new strategy for myopia treatment to restore normal scleral structure and function and slow or prevent myopia progression." (PMID 40933557, 2025). "By reducing HIF-1α levels, these processes may be mitigated, thereby inhibiting myopia progression." (PMID 40933557, 2025). "They include trans differentiation of HIF-1α and HSFs, increased expression of matrix metalloproteinase-2 and α-smooth muscle actin, and decreased expression of type I collagen α1 protein, which jointly affect myopia through a bidirectional effect with scleral hypoxia and scleral remodeling." (PMID 36961150, 2023). "Subsequent experimental validation confirmed the HIF-1α-induced down-regulation of NAT2 in myopic sclera and demonstrated that genetic modulation of NAT2 expression in murine sclera directly influenced myopia progression." (PMID 41169617, 2025). "The reduced concentrations of HIF-1α and VEGF observed in highly myopic eyes appear consistent with previous reports indicating diminished angiogenic signaling in advanced myopia." (PMID 41438149, 2025). "The integration of clinical imaging and aqueous humor profiling supports the potential of HIF-1α and PDGF-BB as biomarkers and therapeutic targets in pathological myopia." (PMID 41438149, 2025). "Molecular profiling revealed lower levels of HIF-1α and VEGF (p < 0.01), and elevated levels of PDGF-BB (p < 0.05), HGF, and IL-6 (p < 0.01) in the high myopia group." (PMID 41438149, 2025). "Among these, our findings identify HIF-1α and PDGF-BB as key contributors to the progression of myopia." (PMID 41438149, 2025). "Overall, these findings illustrated that NAT2 was the direct trans-repression target of HIF-1α in scleral fibroblasts under hypoxia, which suggested the mechanism that NAT2 was down-regulated in myopia." (PMID 41169617, 2025).
myopia (continued). "For the first time, this study identifies significant alterations in HIF-1α and PDGF-BB levels in high myopia, with consistent correlations to key clinical parameters such as axial length, choroidal thickness, and maculopathy severity." (PMID 41438149, 2025). "Bendazol can inhibit the development of form-deprivation myopia (FDM) and the upregulation of HIF-1α." (PMID 38443979, 2024). "It was reported that Hif-1α could activate MAPK signaling and thereby stimulate scleral collagen remodeling in pathologic myopia." (PMID 36975502, 2023). "Under the hypoxic condition, VEGF expression is induced through the activation of HIF-1α signaling and activates choroid endothelial cells to initiate myopic CNV, which could accelerate the progression of myopia." (PMID 37355654, 2023). "Although its relationship to myopia is not readily apparent from these functions, a prior study suggested that HSP90 could upregulate the expression of Hypoxia Inducible Factor 1 Subunit Alpha (HIF1α) in senescent ARPE-19 cells and subsequently promote the induction of distinct inflammatory factors." (PMID 35153787, 2022).
brain tumors (27 papers, 2010 to 2026). "It has been reported that overexpression of HIF‐1α caused treatment failure and a poor prognosis of brain tumors." (PMID 32533646, 2020). "It should encourage further evaluation of hypericin in brain tumors and other cancer types in which high HIF-1α levels cause clinical exacerbation." (PMID 21949677, 2011). "The results we show here highlights the importance of hypoxic mechanism in brain tumours and the high level of overexpression of angiogenic factors as HIF1A, VEGFA, and MMP2 that are implicated in metastasis could be target molecules in those tumour types." (PMID 22570651, 2012). "In these brain tumours, loss of WWOX expression removes repression of pro-invasive genes such as MMP1, thereby facilitating HIF1A-driven ECM remodelling, which exacerbates tumour aggressiveness and further undermines genomic stability." (PMID 41007296, 2025). "Overall, our findings support the theory that ACF disrupts HIF-1α transcriptional activity and impairs the HIF-1α-mediated survival pathways of brain tumor cells." (PMID 29097800, 2017). "This study reports preclinical evidence that this safe, small molecule can contribute to brain tumor therapy and highlights the significance of HIF-1α-targeting molecules." (PMID 29097800, 2017). "The Id2 gene is also a target for HIF1α and HIF2α, making it part of a positive feedback loop mechanism, at least in models of brain tumor." (PMID 27144179, 2016). "Understanding these coupled pathways reveals vulnerable nodes such as HIF1α signaling, α-KG-dependent demethylation, and lactate-driven epigenetic remodeling that may be exploited for targeted treatment of metastatic brain tumors." (PMID 41799524, 2026). "In this study, our data suggest that the mRNA expression level of HIF1α was higher in organs such as the brain tumors, gastrointestinal tumors (esophagus, pancreas, stomach, and gallbladder), and lung tumors compared with normal tissues, both at the tissue level and the cell line level." (PMID 35860430, 2022). "Additionally, we observed the influence of the WWOX/HIF1A axis in brain tumours." (PMID 41007296, 2025). "It has been suggested that one of the mechanisms able to determine brain tumour progression may be represented by hypoxia, determining the activation of the hypoxia-inducible factor 1-alpha (HIF-1α), which induces autophagy through the transcription regulation of autophagic genes." (PMID 37174088, 2023). "In this case, the serially enriched brain-competent isogenic CTCs may reflect selection pressure for pre-existing cells with elevated hypoxic signaling, although we cannot exclude additional induction of HIF1A activity during the process of brain tumor initiation." (PMID 33298946, 2020). "We also showed that high WWOX/HIF1A ratios promote apoptosis and metabolic stability while suppressing EMT in brain tumours (GBM/LGG)." (PMID 41007296, 2025). "Correspondingly, IHC analysis of the removed mouse brain tumor sections confirmed the high expression of FBXO22, HIF-1α and VEGFA and low expression of VHL in the U87-FBXO22 group compared with the U87-Vector group." (PMID 38519492, 2024). "The main target of this study was to assess the circulating serum hypoxia biomarkers HIF-1α, VEGF, osteopontin, erythropoietin, caveolin-1, GLUT-1, and LDH pre- and post-radiotherapy in patients with brain tumors." (PMID 36121548, 2022). "In this study, we demonstrate that PFKP promotes EGFR activation-induced VEGF expression in HIF-1α-dependent and -independent manners in GBM cells, leading to enhanced blood vessel formation and brain tumor growth." (PMID 36435833, 2022).
brain tumors (continued). "The aim was to assess the serum hypoxia biomarkers HIF-1α, VEGF, osteopontin, erythropoietin, caveolin-1, GLUT-1, and LDH pre- and post-radiotherapy in patients with brain tumors." (PMID 36121548, 2022). "High circulating glucose levels accelerate brain tumor growth and angiogenesis while also preventing apoptosis through activation of the IGF-1/PI3K/Akt/Hif-1a signalling pathways." (PMID 20412570, 2010). "For example, a study has found that HIF1α promotes EPO expression at the transcriptional level under hypoxia and achieves antitumor effects by regulating Epo-activated signaling pathways as interfering with the cell cycle of brain tumors." (PMID 35860430, 2022). "In addition to enrichment of HIF1A signaling, several other signaling pathways (SREBP1, E2F, AP2, NFY, and CDPCR3) also demonstrate enrichment in brain tumor samples across both our mouse and patient analyses." (PMID 33298946, 2020). "Here we used 1% O2 for hypoxic conditions as this level can induce a hypoxic response (increased levels of HIF-1α) without affecting cell proliferation or survival in a range of brain tumour cell lines." (PMID 30943920, 2019). "Other studies demonstrated that HIF-2α appears to be an attractive target because it is specifically expressed by brain tumor stem cells but not neural progenitor cells, whereas HIF-1α is up-regulated in these cellular populations." (PMID 22140506, 2011). "However, it has been shown that in certain brain tumors, distance from the vasculature or varied levels of hypoxia was not always the sole mediator of increased levels of HIF1α." (PMID 40806669, 2025).
cyst (27 papers, 2007 to 2026). A sac-like closed membranous structure that may be empty or contain fluid or amorphous material. "Apical ATP release is elevated in PKD1-deficient cyst-forming cells following pharmacological induction of HIF-1α and attenuated by two Pannexin-1 inhibitors, Probenecid and Brilliant Blue FCF (BB-FCF)." (PMID 42117913, 2026). "In this regard, stress-induced transcription factor Hif1α has been implicated in cyst development and enhanced autophagy in a rat model of polycystic kidney disease." (PMID 34948309, 2021). "HIF-1α promoted calcium-activated chloride secretion but was also associated with increased cyst cell proliferation, especially in a rapid progressive ADPKD mouse model." (PMID 32885302, 2020). "However, the mechanisms underlying ATP release into the cyst fluid and the role of HIF-1α in cyst enlargement remain incompletely understood." (PMID 42117913, 2026). "In conclusion, HIF-1α promotes Pannexin-1 expression in cyst-lining cells, facilitating directional ATP release into the cyst lumen and driving ATP-dependent cyst expansion." (PMID 42117913, 2026). "The authors of another study found that HIF-1α activation leads to increased chloride secretion in cystic epithelial cells, contributing to cyst enlargement." (PMID 40722668, 2025). "The present study found that HIF-1α is expressed in both the cytoplasm and nucleus of immunopositive radicular cyst cells, with the nucleus being the most abundant." (PMID 39657933, 2025). "Genetic deletion of Hif-1α significantly attenuated cyst growth, indicating its role in disease progression." (PMID 40722668, 2025). "Although HIF2αKD affected expression of hypoxia response genes, our data suggests that HIF2α function is different from that of HIF1α as HIF2α appears to participate in the regulation of cyst morphogenesis also in normoxia." (PMID 38802496, 2024). "At these stages, we have shown that HIF-1α is detrimental by further promoting cyst growth, particularly by activation of calcium-activated chloride secretion." (PMID 37206967, 2023). "The MIF inhibitor ISO-1 attenuates HIF-1α- and cAMP-dependent cyst enlargement and can also be used as a therapeutic target to delay cyst growth in ADPKD." (PMID 37241147, 2023). "HIF-1α then promotes cyst enlargement by transcriptional activation of target genes which mediate calcium-activated chloride secretion like the purinergic receptor P2Y2R whose stimulation leads to activation of the chloride channel TMEM16A." (PMID 37206967, 2023). "ADPKD kidneys, at least at later stages of the disease, are characterized by regional hypoxia leading to upregulation of HIF-1α in the cyst epithelium." (PMID 37206967, 2023). "In ADPKD, continuous cyst growth is accompanied by regional tissue hypoxia in the kidneys, which leads to upregulation of hypoxia-inducible transcription factor (HIF-1α) in cyst-lining cells." (PMID 37206967, 2023). "Cyst growth leads to the compression of intact tissue, leading to hypoxia, which was evident in our model as shown by HIF-1α staining in the cyst epithelium." (PMID 35892566, 2022). "HIF-1α appears to be an important mediator and accelerator of cyst growth, and has a strong cyst-growth-promoting effect in ADPKD mouse models, especially in severe phenotypes of ADPKD." (PMID 35892566, 2022). "HIF1α is absolutely required for the initial dysplasia and cyst formation that defines the early stages of tumorigenesis while both HIF1α and HIF2α are required for overt carcinoma." (PMID 36040300, 2022). "Pharmacological stabilization of HIF-1α resulted in significant increase of MIF in cyst epithelial cells whereas tubule-specific knockout of HIF-1α prevented MIF upregulation." (PMID 32885302, 2020). "Since cyst expansion aggravates regional hypoxia which then induces HIF-1α, a feedforward loop is established that accelerates cyst expansion and disease progression." (PMID 32885302, 2020).
cyst (continued). "Continuous cyst enlargement leads to progressive tissue hypoxia which induces HIF-1α in cyst epithelial cells." (PMID 32885302, 2020). "Next to HIF-1α, we also found cAMP which is a main driver of cyst growth in ADPKD as an additional regulator of MIF expression." (PMID 32885302, 2020). "MIF is regulated by HIF-1α as well as cAMP, both of which have been shown to promote cyst enlargement in PKD." (PMID 32885302, 2020). "We have previously shown that cyst growth is accompanied by regional hypoxia, which induces HIF-1α in cyst-lining cells which then promotes cyst growth primarily through induction of genes that mediate calcium-activated chloride secretion." (PMID 32885302, 2020). "Ablation of Hif1α in a Fh mutant background exacerbated cyst formation, an opposite phenotype to that expected if the premalignant lesions were consequences of Hif1α induction." (PMID 25126540, 2014). "Hypoxia-inducible factor-2α appears to become progressively more evident than HIF-1α in foci of renal dysplasia, cyst formation and frank tumours." (PMID 17505508, 2007). "Moreover, the induction of hypoxia-inducible factor 1α (HIF-1α) in cyst-lining epithelial cells further enhances chloride conductance." (PMID 42117913, 2026). "SGLT2 inhibition may also upregulate HIF-1α in collecting ducts, possibly contributing to cyst expansion." (PMID 40214869, 2025). "HIF1α upregulation in hypoxia was documented to activate the TGFβ-pathway via upregulation of BAMBI eventually leading to loss of epithelial polarity and HIF1αKD rescued normal cyst formation in hypoxic conditions." (PMID 38802496, 2024). "Signaling pathways being related to the activation of HIF-1α during hypoxia could be contributing to cyst expansion in PKD." (PMID 38397444, 2024). "In addition, tubular hypoxia inducible factor 1α (HIF-1α) was described as having a strong cyst-growth-promoting effect in ADPKD mice." (PMID 37241147, 2023). "In addition, tubular hypoxia inducible factor 1α (HIF-1α) is described to have a strong cyst growth-promoting effect in ADPKD mice." (PMID 34206927, 2021). "Notably, deletion of Pkd1 results in upregulation of hypoxia-inducible factor (HIF)-1α, which worsens cyst formation." (PMID 32859916, 2020). "However, we also found HIF-1α-dependent increase of cyst cell proliferation in vivo, which was especially pronounced in a rapid progressive ADPKD mouse model." (PMID 32885302, 2020). "HIF-1α stabilization by the prolyl-hydroxylase inhibitor ICA did not only result in an increase of MIF protein in cyst-lining cells but also induced cyst growth which could be inhibited by the MIF-inhibitor ISO-1." (PMID 32885302, 2020). "• MIF-inhibitor ISO-1 reduces HIF-1α- and cAMP-dependent cyst growth." (PMID 32885302, 2020). "Induction of HIF-1α by ICA resulted in a significant cyst progression which could be rescued by tubular deletion of HIF-1α." (PMID 32885302, 2020). "Interestingly, when comparing the basal and parabasal layers of OKC, we observed predominant staining of NOTCH1 and HIF-1α in the epithelial layers near to the cyst lumen." (PMID 31319505, 2019). "We hypothesize that compression induced localized ischemia‐hypoxia of normal epithelia near a cyst leads to local stabilization of HIF‐1α, leading to altered transepithelial transport that encourages cyst expansion." (PMID 29263117, 2017). "Since loss of all three Phds in the kidney failed to induce cyst formation, despite the increased levels of Hif-1α, we conclude that cystogenesis in Fh1-deficient mice is both Hif and Phd independent." (PMID 22014577, 2011). "Interestingly, Hif1α deletion attenuated cyst progression in an ADPKD mouse model." (PMID 34948309, 2021). "However, recently, we have shown that stimulation of HIF-1α (the isoform present in tubular and cyst-lining cells) may be detrimental by significantly promoting cyst growth in an ADPKD mouse model." (PMID 32885302, 2020).